BMI1 (BMI1 proto-oncogene, polycomb ring finger)
Diseases named in the same sentence as BMI1 in open-access papers (continued):
Sharing a sentence is not in itself a finding about the gene and the disease.
chronic myelogenous leukemia (11 papers, 2014 to 2024). "We next determined the effect of these compounds on reducing the protein levels of BMI1, RING1B, EED, and H2AK119ub in K562 cells, a chronic myelogenous leukemia cell line." (PMID 36737841, 2023). "The Polycomb gene BMI1 expression exerts a negative predictive impact on several hematological malignancies, such as acute and chronic myeloid leukemia (CML), myelofibrosis, and follicular lymphoma." (PMID 30574454, 2018).
tongue cancer (11 papers, 2011 to 2024). A malignant neoplasm affecting the tongue. "We and others have provided evidence that several members of PcG such as EZH2 and Bmi1 are aberrantly upregulated in tongue cancer and associated with aggressiveness and poor prognosis." (PMID 28228691, 2017). "The molecular mechanisms that underlie the regulation of tongue cancer stem cells by Bmi1 need to be investigated." (PMID 28004815, 2016). "Further studies are required to clarify the relationship between these cancer stem cells and Bmi1+ LESCs and to identify the cells of origin in tongue cancer." (PMID 28004815, 2016). "In this study, we adopted the multicolor lineage tracing method to analyze the role of Bmi1-positive cells in a mouse model of chemically induced tongue cancer." (PMID 28004815, 2016). "Moreover, elevated BMI1 is related to cervical node metastasis, high Ki-67 level, and shortened OS, and also acts as an independent prognostic factor for patients with tongue cancer." (PMID 38254031, 2024). "Bmi1‐positive lingual epithelia could serve as CSCs and were considered to be the origin of tongue cancer." (PMID 29479858, 2018). "Thus, we propose that at least some Bmi1+ tumorigenic cells behave as tongue cancer stem cells in developing tumors." (PMID 28004815, 2016). "To determine whether Bmi1-positive cells in tongue cancer serve as cancer stem cells, we used the gene-specific multicolor lineage tracing method to test if Bmi1-positive cells form patches in mice with tongue cancer as well as in RosacreERT2/rbw mice." (PMID 28004815, 2016). "However, the precise role of LESCs in generating tongue tumors and Bmi1-positive cell lineage dynamics in tongue cancers are unclear." (PMID 28004815, 2016). "By labeling Bmi1+ cells in Bmi1creER/+/Rosa26rbw/+ mice prior to inducing carcinogenesis, we examined whether tongue cancer originated from Bmi1+ LESCs." (PMID 28004815, 2016). "Furthermore, miR-200b and miR-15b regulate cisplatin-induced EMT by targeting B lymphoma Mo-MLV insertion region 1 homolog (BMI1) in human tongue cancer cells." (PMID 25638153, 2015). "In contrast, Hayry V, etc. reported that Bmi1 protein expression didn’t correlate with any clinical and histopathological parameters and its negative expression served as adverse prognostic factor in patients with primary T1N0M0 tongue cancers." (PMID 29200967, 2017). "Although many Bmi1-positive cells within the tongue cancer specimens failed to proliferate, some proliferated continuously and supplied tumor cells to the surrounding area." (PMID 28004815, 2016). "However, a recent study showed a significant correlation between negative Bmi-1 protein expression and the recurrence of tongue cancer." (PMID 20936121, 2011).
adenoma (10 papers, 2009 to 2021). A neoplasm arising from the epithelium. "In the papillary and adenoma tissues, BMI-1 was overexpressed (1.047-fold and 1.042-fold) in comparison to healthy tissues (p < 0.05 for both comparisons)." (PMID 34551814, 2021). "In summary, the results of this study have shown that the BMI-1 gene was upregulated in thyroid papillary carcinoma and adenoma tissues compared to adjacent healthy tissue." (PMID 34551814, 2021). "The present study was aimed to evaluate the expression of the B cell-specific Moloney murine leukemia virus integration site 1 (BMI-1) gene in papillary carcinoma, adenoma, and adjacent healthy thyroid tissues." (PMID 34551814, 2021). "Comparison of BMI-1 mRNA level in papillary carcinoma or adenoma tissues to adjacent healthy tissues revealed that BMI-1 was slightly overexpressed in both tissues (p < 0.05 for both comparisons)." (PMID 34551814, 2021). "In this retrospective cross-sectional study, we sought to determine the expression level of the BMI-1 gene in adenoma, papillary carcinoma, and adjacent healthy tissues." (PMID 34551814, 2021). "Here, we showed, using the multicolor lineage-tracing method and mouse models of intestinal adenocarcinoma and adenoma that Bmi1- or Lgr5- positive tumorigenic cells clonally expanded in proliferating tumors." (PMID 28176811, 2017). "Because of the restricted life span of Bmi1 gene ablated mice we took advantage of the higher incidence and shorter latency of the BXB11 founder line to examine the Bmi1 dependence of adenoma growth in advanced disease." (PMID 19156217, 2009). "In the current study we employed two transgenic founder lines with lung targeted expression of C-RAF BXB for the dependence of adenoma initiation and growth on the stem cell self-renewal factor Bmi1." (PMID 19156217, 2009). "Though reduced in size the tumors in Bmi1−/−BXB11 lungs showed features of SP-C C-RAFBXB induced adenomas as judged by analysis of cell morphology and staining with two tumor markers (pan-cytokeratin and pro SP-C)." (PMID 19156217, 2009). "TUNEL staining showed a significant increase in the apoptotic cell ratio in adenomas of three months old Bmi1−/−BXB11 mice." (PMID 19156217, 2009). "Consequently, the present study is aimed to investigate the level of expression of the BMI-1 gene in human adenoma, papillary thyroid carcinomas, and their healthy adjacent tissue samples." (PMID 34551814, 2021). "Results of the Dunnett test revealed that the BMI-1 gene was overexpressed in adenoma tissues by 1.042-fold (CI − 0.08533 to − 0.0003886, p = 0.04) and in papillary carcinoma tissues by 1.047-fold (CI − 0.09009 to − 0.005150, p: 0.02) compared with the adjacent healthy tissues." (PMID 34551814, 2021). "Supporting a role for Jag1 in adenoma formation and by extension in tumor-initiating cell (TIC) activity, Jag1 KO adenomas expressed reduced levels of Lgr5, Bmi1, Ephb2, c-Myc, Sox9, and Cd133 compared to the Jag1 WT, as determined by qRT-PCR and in situ hybridization (ISH)." (PMID 30065304, 2018). "Thus, the expression of Bmi-1 protein was significantly higher in the UCC group than in the adenoma and normal controls (P<0.05)." (PMID 23691455, 2012). "In this study we set out to evaluate Bmi1 function in RAF induced adenoma formation." (PMID 19156217, 2009). "This indicates that apoptosis is a late event in Bmi1−/−BXB11 adenomas." (PMID 19156217, 2009). "ISC-specific deletion of both adenomatous polyposis coli (APC) alleles using either Bmi1-, CD133-, or LGR5-Cre recombinase mice leads to a rapid full adenoma formation, while a similar APC deletion in late progenitors or differentiated cells only results in sporadic and slow-developing adenoma." (PMID 33916891, 2021). "Depletion of Bmi1 in both the BXB23 and BXB11 background led to a pronounced decrease in tumor growth rate and an increase in cell death within the adenomas." (PMID 19156217, 2009).
adenoma (continued). "Based on the observation, that Bmi1 is expressed in the C-RAF BXB initiated lung adenomas and that Bmi1 is a target of RAF signaling we decided to investigate adenoma formation in the absence of Bmi1." (PMID 19156217, 2009). "We show that BXB11 has a four fold higher incidence and shorter latency of adenomas allowing examination of advanced disease in the absence of Bmi1." (PMID 19156217, 2009). "Interestingly, Bmi1 expression was not apparent in adenomas from either group of animals, whereas patches of strong immunoreactivity were found in infiltrating cells from CDX2;APC mice." (PMID 30150766, 2018). "In agreement with previous reports showing p19ARF up-regulation in response to oncogenic hyperproliferative signals, expression of p19ARF was not restricted to the Bmi1−/− background but could also be observed to a lesser extent in BXB11 adenomas." (PMID 19156217, 2009). "This distribution could not be observed in Bmi1−/−BXB11 adenomas where p19ARF localized throughout the nucleus in many distinct spots." (PMID 19156217, 2009).
B-cell lymphoma (9 papers, 2010 to 2024). "BMI1 has been recognized as a proto-oncogene that encodes a protein consisting of 324 amino acids, is primarily localized in the nucleus, and has been implicated in the development of mouse pre-B-cell lymphomas." (PMID 38515119, 2024). "Bmi-1 was first identified as a protein that cooperatively promotes tumorigenesis with c-Myc in B-cell lymphoma." (PMID 38141761, 2024). "Bmi-1 was first identified as a proto-oncogene that cooperated with c-Myc in generating pre-B-cell lymphomas in a murine model." (PMID 20377880, 2010). "Furthermore, the low expression of Survivin is considered to be one of the factors for the success of chemotherapy; Bmi-1 promotes the drug resistance of B-cell lymphoma cells through the regulation of Survivin." (PMID 35897796, 2022). "Bmi-1 (B-cell-specific Moloney murine leukemia virus integration site 1) was originally isolated as an oncogene that cooperates with c-myc in the generation of mouse pre B-cells lymphomas." (PMID 20809956, 2010).
esophageal cancer (9 papers, 2010 to 2023). A primary or metastatic malignant neoplasm involving the esophagus. "Since CA9 was recently reported to play an important role in breast cancer stem cell survival, we investigated the association of BMI1 with CA9 in esophageal cancer." (PMID 26156831, 2015). "Circ-BMI1 induction resulted in reduced proliferation and migration of tumor cells, implying its potential implementation in esophageal cancer diagnosis and treatment." (PMID 34771517, 2021). "Overall, these data indicated the potential clinical significance of Bmi1 in esophageal cancer patients." (PMID 32884573, 2020). "According to the data of The Cancer Genome Atlas (TCGA) database, the expression level of Bmi1 mRNA in esophageal carcinoma (ESCA) was upregulated in the esophageal carcinoma tissues compared with normal tissues." (PMID 32884573, 2020). "According to TCGA public database GEPIA, BMI1 level was upregulated in ESCA (esophageal carcinoma) tissues, and ESCA patients in terminal stage (IV) presented higher BMI1 level than those in earlier stages (I‐II)." (PMID 32239639, 2020). "In our study, we first confirmed the high expression of Bmi1 in esophageal carcinoma and patients with high expression prone to malignant transformation." (PMID 32884573, 2020). "Our previous study demonstrated that Bmi1 expression was similar to Ki-67 expression in their distribution in the basal layer of normal squamous epithelium and extending to full thickness in esophageal carcinoma." (PMID 27476776, 2016). "We also demonstrated the percentage of MCM4 and MCM7 expression to be significantly correlated with Ki-67, Bmi1, and cyclin E expression in esophageal carcinoma and precancerous lesions." (PMID 27476776, 2016). "In summary, our findings demonstrated the percentages of MCM4 and MCM7 expression significantly correlated with Ki-67, Bmi1, and cyclin E expression in esophageal carcinoma and precancerous lesions." (PMID 27476776, 2016). "MCM4 and MCM7 expression had similar distribution as Ki-67 and Bmi1 expression in esophageal carcinoma and pre-cancerous lesions." (PMID 27476776, 2016). "Western blotting analysis showed that Bmi-1 protein was highly expressed in four esophageal cancer cell lines (108CA, Kyse 140, Eca-109 and TE-1) and HPV E6/E7 induced immortalized cell line NE-3, whereas it was weakly detected in normal esophageal tissue." (PMID 20809956, 2010). "This is the first study showing the expression of Bmi-1 in esophageal cancer cell lines as well as tumor tissue, highlighting the clinical significance of Bmi-1 in esophageal carcinoma." (PMID 20809956, 2010). "The expression level of Bmi-1 protein in esophageal carcinoma was significantly correlated with patients' survival time (P = 0.015), that was the higher level of Bmi-1 expression correlated with shorter survival time." (PMID 20809956, 2010). "Along the same lines, circ-BMI1 was also recently found deregulated in esophageal cancer." (PMID 34771517, 2021). "In this study, therefore, we retrospectively investigated the expression of BMI1 protein in human oesophageal cancer tissues and evaluated the clinical implications of aberrant BMI1 activation for these patients who underwent preoperative CRT and oesophagectomy." (PMID 23046527, 2012). "The presence of Bmi-1 autoantibodies in sera from patients with ESCC may have potential clinical utility in esophageal cancer diagnosis." (PMID 20809956, 2010). "We have shown that the expression of Bmi-1 is closely associated with advanced stage and lymph node metastatic status of esophageal cancer patients, which is strongly suggesting that Bmi-1 can be used as a marker to identify subsets of ESCC cancer patients with more aggressive feature." (PMID 20809956, 2010). "The presence of Bmi-1 autoantibodies in sera from patients with ESCC may have clinical utility in esophageal cancer diagnosis." (PMID 20809956, 2010). "Higher expression of Bmi-1 was observed in invasive front of esophageal carcinoma tissue." (PMID 20809956, 2010).
esophageal cancer (continued). "However, further studies are needed to clarify the mechanism by which Bmi-1 is involved in the development and progression of esophageal carcinoma and its exact role in the regulation of carcinogenesis in esophageal carcinoma." (PMID 20809956, 2010). "Thus, our findings indicate that Bmi-1 protein expression level has a significant correlation with prognosis of esophageal carcinoma." (PMID 20809956, 2010). "In this study, we investigated CA9 expression in esophageal cancers and in precancerous lesions and explored the association of CA9 expression with prognostic factors and with stem cell and tumorigenesis-related markers including BMI1, cyclin E, ki67, MCM4 and MCM7 expression." (PMID 26156831, 2015). "We next determined whether Bmi-1 is overexpressed in esophageal carcinoma samples." (PMID 20809956, 2010). "Bmi-1 might be used as a valuable prognostic marker for esophageal carcinoma patients." (PMID 20809956, 2010). "No data are currently available on the role of BMI1, a candidate downstream target of the Hh pathway, in oesophageal cancer progression after CRT." (PMID 23046527, 2012). "Sera from 62 of 159 esophageal cancer patients (39.0%) were reactive with recombinant Bmi-1 in ELISA, whereas none of the control sera from healthy volunteers recognized Bmi-1." (PMID 20809956, 2010). "We demonstrated that BMI1 positivity indicative of PcG protein chromatin silencing pathway activation was significantly correlated with oesophageal cancer recurrence and poor prognosis after CRT, and that it was not inversely correlated with the presence of the downstream target p16INK4A." (PMID 23046527, 2012). "Huang D and others found that stem cell-related genes (including OCT-4, SOX-2, BMI-1, and ZFX) were upregulated in SP(side population) cells of human esophageal carcinoma 9706 cells compared with non-SP cells." (PMID 22185393, 2011).
Alzheimer disease (8 papers, 2019 to 2025). A progressive, neurodegenerative disease characterized by loss of function and death of nerve cells in several areas of the brain leading to loss of cognitive function such as memory and language. "Numerous studies have consistently demonstrated that decreased expression of Bmi-1 in brain tissue is associated with degenerative brain diseases such as Alzheimer’s disease (AD) and Parkinson’s disease (PD)." (PMID 40153371, 2025). "Proteins involved in the PI3K/AKT pathway as well as mitochondrial regulator proteins (widely studied in aging-associated diseases such as Parkinson’s disease and Alzheimer’s disease) were evaluated after BMI1 silencing to further elucidate the mechanism by which BMI1 acts in mitochondrial function." (PMID 35431986, 2022). "Accumulating evidence suggests that BMI1 confers protective effects against Alzheimer’s disease (AD)." (PMID 34610832, 2021). "Along those lines, the Notch transcriptional target BMI1 is a major regulator of ARF expression in development, known to hold a neuroprotective role against degenerative disorders such as Alzheimer’s disease." (PMID 33445626, 2021).
Ewing sarcoma (7 papers, 2011 to 2024). A small round cell tumor that lacks morphologic, immunohistochemical, and electron microscopic evidence of neuroectodermal differentiation. "BMI1 has also been studied in pediatric cancers such as medulloblastoma and Ewing sarcoma, but its possible role in RMS has not yet been identified." (PMID 33523558, 2021).
laryngeal carcinoma (7 papers, 2012 to 2024). Carcinoma that arises from the laryngeal epithelium. "BMI1 knockdown decreased the proliferation, invasion, and stem cell-like characteristics of laryngeal cancer cells." (PMID 39452555, 2024). "Our previous study has confirmed proto-oncogene Bmi-1 as a key regulator for self-renewal of laryngeal cancer stem cells." (PMID 38095348, 2023). "Targeted knockdown of Bmi-1 gene effectively inhibited the self-renewal and differentiation of laryngeal cancer stem cells, leading to the promoted sensitivity to chemotherapy including paclitaxel." (PMID 38095348, 2023). "The expression of BMI-1 in patients with laryngeal carcinoma seems to be a potential marker of tumor aggressiveness." (PMID 23031716, 2012). "The objective of this study was to evaluate immunohistochemically the expression of BMI-1 in laryngeal carcinomas and to determine its clinical significance." (PMID 23031716, 2012). "BMI1 expression was discovered to be elevated in laryngeal cancer tissues and cell lines." (PMID 39452555, 2024). "In addition, cRGD peptide, paclitaxel and Bmi-1 siRNA in the nanoparticles showed synergistic effects to suppress laryngeal cancer stem cells." (PMID 38095348, 2023).
lung adenocarcinoma (7 papers, 2013 to 2023). A carcinoma that arises from the lung and is characterized by the presence of malignant glandular epithelial cells. "First, we treated A549 cells, a lung adenocarcinoma cell line, with metformin and examined the expression of Bmi-1." (PMID 26717043, 2016). "Similar findings were observed in lung adenocarcinomas and appeared that the expression of Bmi-1 was correlated with pathological grades of the cancer, where opposite changes were found in p-AMPK." (PMID 26717043, 2016). "BMI1 is known as a critical molecule related to EMT and cancer stemness, and we identified BMI1 as one of the molecules inducing chemoresistance in lung adenocarcinoma cells." (PMID 37190178, 2023). "There are several mechanisms proposed which could affect BMI1 expression: A very recent report showed C/EBPα protein contributes to inhibit BMI1 expression, suggesting anti-BMI1 inhibition may provide new therapeutic option for lung adenocarcinoma patients with low C/EBPα and high BMI1 expression." (PMID 28445986, 2017). "Previous studies have reported that knocking down of endogenous Bmi-1 diminishes secretion of VEGF from lung adenocarcinoma cells in vitro, leading to promoted angiogenesis in lung adenocarcinoma." (PMID 23383216, 2013). "With regard to translational relevance, PTC-209 is a small molecule inhibitor of BMI1 expression that has shown preclinical activity against colorectal and lung adenocarcinomas; however, to our knowledge, there are no clinically available BMI1 inhibitors." (PMID 29050200, 2017).